CXCR1 (C-X-C motif chemokine receptor 1)
Diseases named in the same sentence as CXCR1 in open-access papers (continued):
Sharing a sentence is not in itself a finding about the gene and the disease.
asthma (18 papers, 2009 to 2025). "In autoimmune diseases, CXCL3-induced migration becomes exclusively CXCR1-dependent, which underlines the significance of CXCR1 in the pathogenesis of airway remodeling associated with asthma." (PMID 37709757, 2023). "In contrast, in asthmatic ASMC, CXCL3-induced migration becomes exclusively CXCR1-dependent, which underlines the significance of CXCR1 in the pathogenesis of airway remodeling associated with asthma." (PMID 26230114, 2015). "Interestingly, CXCR1 coding variants were also described that might be involved in asthma and COPD pathogenesis." (PMID 26230114, 2015). "Although CXCR1 antagonists such as navarixin and reparixin have been developed for asthma, pneumonia, and solid tumors, mAb therapy using anti-CXCR1 has not been explored." (PMID 40109299, 2025). "The other essential point is the implication of CXCL1-CXCR2 signaling-mediated neutrophil suppression in allergic airway inflammation that should be further investigated during the development of CXCR1/CXCR2 inhibition therapy for asthma treatment." (PMID 39767651, 2024). "CXCR1 expression was upregulated in asthma cell models, and interference with CXCR1 expression significantly reduced cell viability." (PMID 36575422, 2022). "The role of CXCR1 in asthma development was preliminarily confirmed." (PMID 36575422, 2022). "This provides another direction for the treatment of severe asthma targeting CXCR1/2." (PMID 33602227, 2021). "In this way, CXCR1/2 inhibition might be a rational therapeutic strategy for severe asthma treatment." (PMID 33602227, 2021). "Recently, a study suggested that KLF2, as a regulator of CXCR1/2, may represent an indicator of asthma severity when combined with CXCR1/2." (PMID 33602227, 2021). "In this work we used a classic model of Th2 eosinophilic airway inflammation, and, an alternative model of Th17 neutrophilic airway inflammation in which mimics to GC-refractory asthma to better understand the role of CXCR1 and CXCR2 receptors in different manifestations of asthma." (PMID 33123138, 2020). "The correlation analysis results showed that CXCR1 (P = 0.02), CXCR2 (P = 0.02), and TLR2 (P = 0.01) were significantly related to asthma severity in GSE43696." (PMID 33602227, 2021). "Nevertheless, the relationship between CXCR1, CXCR2, TLR2 and asthma severity was stable, and combined hub genes were able to discriminate severe asthmatics from mild-moderate asthmatics in ROC analysis." (PMID 33602227, 2021). "In this direction, Danarixin and Navarixin inhibited both CXCR1 and CXCR2 functions in most of the clinical trials of COPD, asthma and influenza infection." (PMID 33123138, 2020). "Inhibition of CXCR1 and CXCR2 by Ladarixin prevented airway hyperreactivity, the main asthma manifestation in those animals." (PMID 33123138, 2020). "Navarixin, a selective CXCR1 and CXCR2 antagonist, was tested in patients with allergen-induced asthma and severe neutrophilic asthma." (PMID 33123138, 2020). "In fact, phase 2 interventional clinical trials on asthma, influenza infection or COPD have been already performed using the CXCR1 and CXCR2 inhibitors." (PMID 33123138, 2020). "Our findings suggest that the chemokine receptors CXCR1, 3 and 4 modulate some aspects of ASM function but their importance in asthma is uncertain." (PMID 19735481, 2009). "Notably, Reperixin displays the ability to target CXCR1, CXCR2, and MMP9, suggesting its potential therapeutic value for managing deteriorating asthma." (PMID 38351296, 2024). "The CTD database was used to predict the underlying therapeutic agents associated with asthma severity, and we noted that Reparixin may have great significance for precision treatment of asthma, targeting MMP9, CXCR1 and CXCR2." (PMID 38351296, 2024). "Furthermore, hub genes, such as CXCR1, CXCR2, and TLR2, were identified as biomarkers of asthma severity through either the neutrophil inflammation pathway or Th17 immune pathway." (PMID 33602227, 2021).
asthma (continued). "There is a growing body of evidence indicating that CXCR1 and CXCR2 may have a role in the pathogenesis of certain pulmonary diseases, including COPD, lung fibrosis and asthma." (PMID 33123138, 2020). "Furthermore, blockade of the murine CXCL8 receptors CXCR1 and CXCR2 reduced neutrophilic airway inflammation in mouse models of various pulmonary conditions including asthma." (PMID 25713319, 2015). "The proportion of primary cultured ASM cells that expressed cell surface CXCR1, 3 and 4 was not different between those subjects with or without asthma." (PMID 19735481, 2009). "This suggests that these chemokine receptors may modulate some aspects of ASM function, but does not support a key role for CXCR1, 3 or 4 in the development of ASM hyperplasia in asthma." (PMID 19735481, 2009).
glioma (18 papers, 2014 to 2025). A benign or malignant brain and spinal cord tumor that arises from glial cells (astrocytes, oligodendrocytes, ependymal cells). "Neutralizing IL-8 or inhibiting its receptor CXCR1/2 potentiates anti-PD-1-mediated antitumor immunotherapy for glioma." (PMID 40362634, 2025). "It has been reported that CXCR1 mRNA expression is significantly higher in patients with glioma than in normal individuals." (PMID 36609243, 2023). "We focused on five CXCR genes, CXCR1/2/3/4/7, which have a significant impact on the overall survival rate of glioma." (PMID 35571062, 2022). "They further demonstrated that IL-8 in an autocrine manner promotes glioma progression by binding to its receptor CXCR1." (PMID 30086759, 2018). "An IL-8 neutralizing antibody as well as a CXCR1 blocking antibody significantly inhibited glioma cell invasion in vitro." (PMID 29644004, 2018). "The migration of MSCs toward a glioma cell line was enhanced also by the overexpression of its receptor chemokine receptor 1 (CXCR1) in MSCs." (PMID 28993773, 2017). "As an example, it has been demonstrated that CXCR1 is involved in UC-MSC migration towards glioma and that overexpression of CXCR1 or CXCR4 in these cells increases their homing into tumors." (PMID 25147818, 2014). "Previous studies have suggested that CXCR1/2/3/4/7 may play a crucial role in gliomas, and have a significant impact on overall glioma survival." (PMID 37626511, 2023). "Moreover, the same authors observed the invasion reduction in glioma cell lines exposed to anti-CXCL8 or anti-CXCR1-neutralizing antibodies." (PMID 31986121, 2020). "This implies that the overexpression of CXCR1 could be a way of improving MSC tropism in glioma therapy." (PMID 28993773, 2017). "In addition, a previous report demonstrated that migration of UCB-MSC towards glioma cells was higher when compared to BM-MSCs likely due to increased levels of the IL-8 receptor, CXCR1, and CXCR2 in the former cell type." (PMID 25147818, 2014). "Blocking CXCL8 or its receptors, CXCR1/2 has been shown to enhance anti-PD-1-mediated antitumor immunity, making CXCL8 a potential target for combination immunotherapy in gliomas." (PMID 41432874, 2025). "Among them, one gene (CXCR5) was downregulated while five other genes (CXCR1, CXCR2, CXCR3, CXCR4, and ACKR3) were enriched in glioma compared with normal brain tissues." (PMID 35571062, 2022). "The significance of up-regulated interleukin-8 (IL-8/CXCL8) and its receptors (CXCR1, CXCR2) levels in glioma was explored by many researcher groups." (PMID 35269652, 2022). "In TCGA database, GBM tissue had higher CXCR1, CXCR2, CXCR4, and CCR5 expression compared with WHO grade II and III glioma." (PMID 34638384, 2021). "Co-expression of the IL-8 receptor, CXCR1/CXCR2, was found to enhance CAR-T cells trafficking and persistence in the tumor in a glioma mouse model." (PMID 33154756, 2020). "Our results indicate that CXCR1/2/3/4/7 may play a significant role in glioma, but there is still a lack of investigation on the exact molecular mechanism of oncogenes involved." (PMID 35571062, 2022). "Several glioma cell lines (D54, LN229, U-87MG and U251) express only CXCR1 but not CXCR2, as already demonstrated." (PMID 31986121, 2020).
Sepsis (18 papers, 2012 to 2025). Sepsis is defined as life-threatening organ dysfunction caused by a dysregulated host response to infection. "More importantly, function studies have shown that the inactivation of the NF‐κB signalling pathway can reduce oxidative stress to allow improvement of ALI; CXCR1/2 antagonists can ameliorate LPS‐induced ALI in association with sepsis." (PMID 34120407, 2021). "Systemic inflammation is known as a hallmark of ACLF; hence the inhibition of CXCR1/2 could prevent systemic inflammation and further development of sepsis." (PMID 33117329, 2020). "The motivation of this work is to use computational modeling of CXCR-1/2 signaling, and the associated dynamics in neutrophil phenotype composition, to explore whether modifying this dynamic could be exploited to favorably impact outcome in sepsis." (PMID 26468651, 2015). "Nevertheless, it has been observed that activation of CXCR1/2 signaling contributes to NET formation in sepsis patients and animal models." (PMID 39328405, 2024). "Considering AKI (acute kidney injury) as a decompensating besides sepsis, we found a decrease in the percentage of neutrophils, CD11b+CD66b+, CXCR1+, and CXCR2+ on CD11b+CD66b+ cells in AKI patients compared to no AKI in decompensated cirrhosis with sepsis." (PMID 35681439, 2022). "Compared to healthy controls, all trauma patient groups had significantly lower neutrophil CXCR1, apart from sepsis patients at day 1 and MOF patients at the postop timepoint." (PMID 34065206, 2021). "In this study a mechanistic computational model was used to evaluate and deploy an extracorporeal sepsis treatment which modulates CXCR-1/2 levels." (PMID 26468651, 2015). "In severe sepsis, an extracorporeal treatment which modulates CXCR-1/2 levels has therapeutic potential, but also potential for harm." (PMID 26468651, 2015). "CXCR1 is one of the major chemokine receptors on polymorphionuclear neutrophils, and the involvement of polymorphionuclear neutrophils in sepsis is well recognized.CLEC4D, a member of Dectin-2 family, functions in resolution of inflammation, possibly through facilitating neutrophil turnover." (PMID 32151258, 2020). "The computational model described in this manuscript provides a physiologic rationale for neutrophil’s CXCR-1/2 mediated activity in sepsis, delivers insight into the overriding mechanisms involved, and suggests that interventions aiming to modulate phenotypic composition are time sensitive." (PMID 26468651, 2015). "Sequence comparison of target receptors for some of these missing sepsis proteins between human and G. gallus showed relatively high conservation (Percent Positive Residues: CXCR1 76.3%, CXCR2 76.5%, C5aR 57.6%) which would argue against the latter possibility." (PMID 26606420, 2015). "Considering that an ALI mouse model induced by intraperitoneal injection of LPS was also employed to induce sepsis, our results suggested that targeting Cxcr1 on splenic Ly6C+ cDC2s might be a valid strategy for the treatment of systemic inflammatory responses." (PMID 40789072, 2025). "In addition, a recent study showed that inhibition of CXCR1/2 by reparixin reduced NET formation, multiorgan injury, and mortality in septic mice without impairing bacterial clearance, which highlights that CXCR1/2 signalling-induced NET formation is a therapeutic target in sepsis." (PMID 37533081, 2023). "CXCR1 and CXCR2 in human neutrophils are well established receptors for the neutrophil chemoattractant, IL-8, and others have shown modulated CXCL1 and chemokine receptor expression by IL-33 in bacterial infections and sepsis in animal models." (PMID 34266437, 2021). "However, the unaltered expression of FPR1 is critical for the perseverance of the functional response to fMLP, compared with the decreased expression of CXCR1 and CXCR2 and the impaired response to its ligand, IL-8, in murine sepsis." (PMID 27144520, 2016).
Sepsis (continued). "Application of cell-penetrating lipopeptides, which block CXCR1- and CXCR2-signaling, reversed the lethal sequelae of sepsis, including multi-organ failure and disseminated intravascular coagulation in mice, indicating that CXCR2 is very important in sepsis." (PMID 22936934, 2012). "In contrast, neutrophil CXCR1 levels are not altered in sepsis patients." (PMID 37048076, 2023). "Furthermore, CXCR1/2 blockade suppresses SIRS in a murine model of sepsis without yielding higher bacterial load." (PMID 33117329, 2020).
glioblastoma (16 papers, 2014 to 2025). The most malignant astrocytic tumor (WHO grade IV). "The CXCR1 signaling promotes proliferation, inhibits apoptosis, and shortens the S phase in DNA-PK+ glioblastoma cells via activation of the ERK1/2 pathway, which can be blocked by CXCR1 knockdown." (PMID 40362634, 2025). "Studies have revealed that IL-8 (also known as CXCL8)/CXC chemokine receptor 1 and 2 (CXCR1/2, also known as IL8R1/2) signaling contributes to tumor cell proliferation, invasion, and neovascularization of glioblastoma." (PMID 40362634, 2025). "Next, we looked at the contributing role of MYT1L to an IL-8- and GROα-CXCR1 signaling loop in glioblastoma cells." (PMID 40362634, 2025). "Quantitative real-time RT-PCR (qRT-PCR) showed that the CXCR1 expression was up-regulated in A-172 and M059K glioblastoma cell lines, which positively correlated with MYT1L protein levels." (PMID 40362634, 2025). "The relationship between the MYT1L protein and CXCR1 mRNA levels was then examined in glioblastoma and neuroblastoma cell lines." (PMID 40362634, 2025). "To see the significance of the IL-8- and GROα-CXCR1 signaling loop in glioblastoma, we determined the expression of GROα, IL-8, CXCR1/2, and the status of ERK1/2 and AKT pathways in 4 brain cancer cell lines." (PMID 40362634, 2025). "Although this is the first report regarding the critical role of DNA-PK/MYT1L in the proliferative IL-8/GROα-CXCR1 signaling loop in glioblastoma, the significant contributing role of IL-8-CXCR1/2 axes in the proliferation and angiogenesis of glioblastoma cells has been demonstrated before." (PMID 40362634, 2025). "IL-8 receptor CXCR1 may be a biomarker for cancer stem cells, including glioblastoma stem cells." (PMID 40362634, 2025). "Moreover, the IL-8/CXCR1/STAT3 pathway is crucial for the maintenance of glioblastoma stem cells." (PMID 40362634, 2025). "IL-8 and/or GROα bind to CXCR1, eventually promoting glioblastoma proliferation via the ERK1/2 pathway that can be blocked by CXCR1 siRNA, suggesting that the activation of the proliferative ERK1/2 pathway in glioblastoma is, at least in part, CXCR1-dependent." (PMID 40362634, 2025). "It is interesting to look at the expression of DNA-PK, MYT1L, and CXCR1 and the levels of phosphorylated ERK1/2 in a large cohort of glioblastoma tissue samples and correlate the levels of these molecules to clinicopathological parameters of this disease." (PMID 40362634, 2025). "CXCR1- and CXCR2 modified CD70 engineered CAR T cells demonstrated increased intratumoral infiltration in glioblastoma in an in vivo model." (PMID 39835140, 2024). "Concomitant expression of the CXCR1 or CXCR4 transgene on CAR-NK cells has also demonstrated enhanced migration to CD19+ hematological tumors, glioblastoma and ovarian tumors." (PMID 37563648, 2023). "CAR-T cells armed with CXCL8 receptors (CXCR1 and CXCR2) markedly enhanced T cells infiltration and led to complete antitumor responses in murine models ovarian cancer, pancreatic cancer, and glioblastoma." (PMID 33381115, 2020). "Starting from these evidences, in this work we first examined the expression of CXCR1/CXCR2 and secreted CXCL8 in human glioblastoma U-87MG cell line and primary cell cultures from post-surgical specimens of glioblastoma patients." (PMID 31986121, 2020). "This study reveals a positive feedback DNA-PK/MYT1L-CXCR1 proliferative signaling loop that contributes to the progression of glioblastoma via the ERK1/2 pathway and provides a novel insight into the role of DNA-PK in the MYT1L-mediated transactivation of CXCR1." (PMID 40362634, 2025). "We hypothesized the existence of a proliferative signaling loop involving CXC chemokines (e.g., CXCL1 and CXCL8) and their receptors (e.g., CXCR1 and CXCR2) in glioblastoma growth." (PMID 40362634, 2025). "Moreover, enhanced levels of IL-8 and its receptors CXCR1 and CXCR2 enhanced CSC migration, growth and stemness properties in glioblastoma." (PMID 27259257, 2016).
glioblastoma (continued). "Previous literature points to a specific expression of CXCR1 and lack of CXCR2 expression in GB cell lines, although we observed that glioblastoma cells also express CXCR2." (PMID 31986121, 2020).
hepatocellular carcinoma (16 papers, 2015 to 2025). A malignant tumor that arises from hepatocytes. "Liver cirrhosis bears a high risk for developing hepatocellular carcinoma, and it might be speculated that increased hepatocyte CXCR1 expression consequent to liver injury could promote pathological hyperproliferation." (PMID 26858343, 2017). "In hepatocellular carcinoma (HCC), FOXC1 facilitates C-C motif chemokine ligand 2 (CCL2) or C-X-C motif chemokine receptor 1 (CXCR1) expression to drive tumor-associated macrophage infiltration and metastasis." (PMID 40416363, 2025). "Mechanistically, TRIB3‐amplified NF‐κB signaling upregulates CXCR1/2 ligands in hepatoma cells, attracting neutrophils that enhance EMT via the OSM‐STAT3 pathway, thereby diminishing sorafenib's efficacy." (PMID 39932456, 2025). "FOXC1 upregulates the expression levels of CCL2 and CXCR1 by directly binding to their promoters in hepatocellular carcinoma cells." (PMID 33968763, 2021). "The elevated expression of CXCR1 accelerates invasion and metastasis of hepatocellular carcinoma cells." (PMID 33968763, 2021). "Also, compared to their wildtype counterparts, hepatoma cells overexpressing TRIB3 exhibited significantly elevated levels of CXCR1/2 ligands." (PMID 39932456, 2025). "Previous studies have confirmed that IL-8 receptors (CXCR1 and CXCR2) are expressed on the surface of hepatoma cells." (PMID 26593962, 2015). "IL-8 activates FoxC1 expression via the PI3K/AKT pathway and via hypoxia-inducible factor 1 alpha, and FoxC1 expression induces CXCR1 and CCL2 transactivation and promotes inflammation in hepatocellular carcinoma (HCC) and the migration and invasion of HCC cells." (PMID 32373221, 2020). "Consistent with this, sorafenib treatment led to increased infiltration of Gr1+ neutrophils in hepatoma tissues, an effect that was absent in TRIB3 knockout hepatoma cells or was suppressed by administration of the CXCR1/2 inhibitor Reparixin." (PMID 39932456, 2025).